CPAP (centrosome assembly and centriole elongation protein)
Diseases named in the same sentence as CPAP in open-access papers (continued):
Sharing a sentence is not in itself a finding about the gene and the disease.
tumor (14 papers, 2012 to 2025). "Our results shed light on a novel mechanism of tumor suppression by the centriole-associated protein CPAP." (PMID 33889303, 2021). "Since we found that pro-EMT and tumorigenic stimuli such as EGF and TGF can cause cellular accumulation of CPAP in OSCC cells, CPAP expression profiles of tumor and normal tissues of HNSCC patients were probed by examining the public data as well as by performing tissue microarray (TMA) analysis." (PMID 33889303, 2021). "The results showed that low-dose DEN (25 mg/kg) treatment resulted in a higher tumor volume and number of tumor nodules in CPAP Tg mice than WT mice mice." (PMID 34686650, 2021). "We found that CPAP protein levels were higher in tumor epithelium of HNSCC patients compared to that of normal epithelium." (PMID 33889303, 2021). "Here, using the OSCC model, we demonstrate a negative regulatory role for CPAP, an essential centriole biogenesis protein, in tumor prevention by keeping the EGFR signaling regulated and EMT at bay." (PMID 33889303, 2021). "Collectively, these observations suggest that CPAP plays a tumor suppressive role by inhibiting the EMT process in OSCC cells." (PMID 33889303, 2021). "We, then, examined the CPAP protein expression pattern in tumor (n = 71) and adjacent normal tissues (n = 65) of HNSCC patients by TMA analysis." (PMID 33889303, 2021). "Our results show that CPAP-overexpressing HCC cells exhibit enhanced tumor growth and metastatic abilities in an orthotopic animal model." (PMID 31511651, 2020). "To identify additional molecules potentially involved in CPAP-mediated metastasis, we analyzed the gene expression pattern in the IL-6-treated GFP-CPAP/Hep3B cells using the human tumor metastasis RT2 ProfilerTM PCR array." (PMID 31511651, 2020). "Functional characterization indicated that CPAP overexpression increases tumor growth, angiogenesis, and metastasis ex vivo and in vivo." (PMID 31511651, 2020). "The results showed that overexpression of CPAP/WT significantly increased tumor growth compared with CPAP/DM." (PMID 31170980, 2019). "However, a role for CPAP as a tumor suppressor in regulating EGFR homeostasis and signaling, and EMT is not known." (PMID 33889303, 2021). "Importantly, the average tumor weights upon euthanasia on day 48 (SCC-Cal27 cell recipients) or day 24 (UM-SCC-74B cell recipients) post-injection were significantly higher in CPAP-shRNA expressing cell recipients." (PMID 33889303, 2021). "Interestingly, CPAP was overexpressed in HCC tissues with a large tumor diameter (≥5 cm), which possess higher metastatic ability, rather than in tumors with a small size (≤2 cm)." (PMID 31511651, 2020). "Importantly, the level of CPAP mRNA was positively associated with the expression of CD44 and IL-8 mRNAs in tumor tissue with vascular invasion." (PMID 31511651, 2020). "Interestingly, both ex vivo and in vivo experimental results indicated that CPAP overexpression promotes tumor growth, metastasis, and angiogenesis by enhancing STAT3 transcriptional activity via direct interactions." (PMID 31511651, 2020). "Furthermore, detection of significantly higher levels of CPAP protein in HNSCC tissues compared to normal tissues, and lack of correlation of CPAP levels with EGFR expression, suggests that tumor associated inflammation contributes to cellular accumulation of potentially non-functional CPAP." (PMID 33889303, 2021). "In addition, CPAP is required for spindle orientation, which defines normal and asymmetric cell divisions, abnormalities in which could lead to various clinical conditions including tumor malignancies." (PMID 33889303, 2021). "Interrupting the interaction between CPAP and STAT3 attenuates STAT3-mediated tumor growth and angiogenesis." (PMID 31511651, 2020). "SUMO-1-modified CPAP enhances the transcriptional activity of NF-κB in HCC cells; overexpressed CPAP directly interacts with STAT3 to enhance IL-6-mediated STAT3 activation and promote HCC tumor growth and metastasis." (PMID 34686650, 2021).
tumor (continued). "Tumor growth was relatively rapid (not shown) in CPAP-shRNA expressing, both SCC-Cal27 (epithelial) and UM-SCC-74B (mesenchymal), cell recipient groups compared to their control-shRNA cell recipient counterparts." (PMID 33889303, 2021). "The level of CD44 mRNA was increased in the tumor parts rather than the adjacent nontumor tissues, and positively correlated with the level of CPAP mRNA in HCC." (PMID 31511651, 2020). "Overall, these observations, along with the lack of correlation between the levels of CPAP and EGFR in OSCC cell lines, suggest that tumor associated inflammation drives cellular accumulation of CPAP which may not be functional in terms of impacting EGFR signaling, EMT and/or tumor suppression." (PMID 33889303, 2021).
cancer (12 papers, 2012 to 2025). A tumor composed of atypical neoplastic, often pleomorphic cells that invade other tissues. "In fact, our results show that EGF and TGF treatments, which are known to promote the EMT and tumorigenic potential of cells, causes the accumulation of CPAP protein in cancer cells." (PMID 33889303, 2021). "The centrosomal protein CENPJ/CPAP is involved in centrosome clustering in cancer cells and antagonizes CP110 during the extension of centriole and cilia." (PMID 35803737, 2022). "It has also been shown that inhibition of CPAP-tubulin interaction prevents the proliferation of centrosome-amplified cancer cells." (PMID 33889303, 2021). "Recently, it has been shown that inhibition of CPAP-tubulin interaction prevents proliferation of centrosome-amplified cancer cells." (PMID 33889303, 2021). "It is well recognized that angiogenesis promotes cancer metastasis; therefore, we examined the angiogenesis-promoting ability by CPAP overexpression." (PMID 31511651, 2020). "CPAP is overexpressed in HCC, and the expression of CPAP is positively correlated with vascular invasion, recurrence after surgery, and cancer staging in HCC." (PMID 31511651, 2020). "Even though the role of CPAP in coordinating these two pathways remains unclear, our results show that CPAP might be an important regulator linking inflammation to cancer development." (PMID 31511651, 2020). "In summary, our findings indicate that CPAP is an important regulator of STAT3-mediated angiogenesis and cancer metastasis; hence, blockage of the interaction between CPAP and STAT3 is a promising strategy for cancer therapy in CPAP-overexpressing HCC cells." (PMID 31511651, 2020). "The interaction between CPAP and HBx can provide a microenvironment to facilitate HCC development via enhancing NF-κB activation, inflammatory cytokine production, and cancer malignancies." (PMID 31170980, 2019).
CPAP also shares sentences with these, for which no sentence is quoted: thyroid cancer (6 papers); Infertility (3); ZIKV infection (3); brain tumours (2); dwarfism (2); Intellectual disability (2); papillary thyroid carcinoma (2); Primordial dwarfism (2); autism (1); ciliopathies (1); glioblastoma (1); infection (1); language disorder (1); Macrocephaly (1); malaria (1); male infertility (1); neurological disorders (1); ovarian carcinoma (1).